TTC4 (tetratricopeptide repeat domain 4)
Description:
Co-chaperone that recruits molecular chaperones Hsp90 (HSC82 and HSP82) and Hsp70 (SSA1) to nascent polypeptides, facilitating their proper folding into functional proteins. Client proteins include eukaryotic elongation factor eEF2, a key player in cellular translation. Stimulates SSA1 ATPase activity, but not Hsp90 ATPase activity (By similarity). Promotes Sendai virus (SeV)-induced host cell innate immune responses.
Synonyms: MGC5097; FLJ41930; CNS1
Tractability: PROTAC: ubiquitination databases record sites on it; its protein half-life has been measured.
Gene: Protein-coding gene on chromosome 1 (54,715,835 to 54,742,657, forward strand). Ensembl gene ENSG00000243725.
Subcellular location: Nucleus; Nucleus, nucleoplasm; Cytoplasm
Subcellular location (Human Protein Atlas): Intermediate filaments; Cytoplasmic bodies
Gene Ontology:
Molecular function: protein binding; Hsp70 protein binding; Hsp90 protein binding
Biological process: defense response to virus; innate immune response; protein folding
Cellular component: cytoplasm; intermediate filament cytoskeleton; nucleus; nucleoplasm
Genetic constraint (gnomAD): Loss-of-function variants: 30 observed, 47.82 expected, observed/expected ratio (o/e) 0.63, 90% interval 0.47 to 0.85. The upper end of that interval is the gene's LOEUF score, 0.85, which puts it in group 3 of 6, group 1 being the genes least tolerant of losing a copy. Missense variants: 390 observed, 443.97 expected, observed/expected ratio (o/e) 0.88, 90% interval 0.81 to 0.95. Synonymous variants: 141 observed, 164.87 expected, observed/expected ratio (o/e) 0.86, 90% interval 0.75 to 0.98.
Homologues: Orthologues: chimpanzee TTC4 (98% identical), macaque TTC4 (97% identical), dog TTC4 (87% identical), guinea pig TTC4 (83% identical), rabbit TTC4 (82% identical), mouse Ttc4 (82% identical), pig TTC4 (82% identical), rat Ttc4 (78% identical), zebrafish ttc4 (59% identical), tropical clawed frog ttc4 (55% identical), Caenorhabditis elegans ttc-4 (32% identical), Drosophila melanogaster Dpit47 (32% identical). Paralogues in human: SPAG1 (17% identical), ST13 (16% identical), SGTA (16% identical), UNC45A (16% identical), RPAP3 (15% identical), SGTB (15% identical), TTC1 (15% identical), UNC45B (15% identical), SPATA16 (15% identical), STIP1 (14% identical), STUB1 (13% identical), TTC31 (13% identical), and 6 more.
Diseases named in the same sentence as TTC4 in open-access papers:
TTC4 is named in the same sentence as 17 diseases in open-access papers, as found by Europe PMC text mining. Sharing a sentence is not in itself a finding about the gene and the disease. The quoted sentences say what the papers report.
malignant melanoma (2 papers, 2008 to 2020). "A role for TTC4 in melanoma had already been suggested, since mutations seen in the gene in patient-derived samples and cell lines, seemed to correlate with increased invasiveness)." (PMID 18320024, 2008). "The gene was originally identified as being localized in a genomic region linked to breast cancer and subsequent studies on melanoma cell lines revealed point mutations in the TTC4 protein that may be associated with the progression of malignant melanoma." (PMID 18320024, 2008). "Our data suggests that in addition to structural changes in the protein, melanoma lines contain more TTC4 protein than melanocytes." (PMID 18320024, 2008). "We show that TTC4 protein levels are raised in malignant melanoma cell lines compared to melanocytes." (PMID 18320024, 2008). "We also present evidence which suggests that TTC4 has a general role in the progression of cancers in addition to melanoma, since the levels of the protein are raised in a variety of tumour cell lines." (PMID 18320024, 2008). "This suggests a possible route through which TTC4 could affect the development of malignant melanoma." (PMID 18320024, 2008).
Autoimmunity (1 paper, 2023). The occurrence of an immune reaction against the organism's own cells or tissues. "We detected strong expression of LTA, TTC4 and UBE2N from the maternal genome and moderate expression of numerous other genes involved in autoimmunity, based on “PubMed” enrichment analysis with STRING17." (PMID 37488170, 2023).
brain tumours (1 paper, 2008). "An increased level of Dpit47 has also been reported in brain tumours in flies A caveat to this argument is that since TTC4 is related to cell stress proteins, it is possible that the increased levels are a response to the abnormal state of the cells." (PMID 18320024, 2008).
breast carcinoma (1 paper, 2008). "The TTC4 gene was originally identified through its localisation in a genomic region linked to breast cancer)-although no mutations could be detected in the gene in this study." (PMID 18320024, 2008).
cardiac hypertrophy (1 paper, 2022). "We found that lncRNA Airn, lncRNA Ttc4, lncRNA Ablim1 and lncRNA Nav3 were novel lncRNAs associated with cardiac hypertrophy." (PMID 35402096, 2022).
cyst (1 paper, 2015). A sac-like closed membranous structure that may be empty or contain fluid or amorphous material. "The morphants of ttc4 and ttc25, a known cilia-related gene, additionally showed pronephric cyst formation." (PMID 25860617, 2015).
Sepsis (1 paper, 2025). Sepsis is defined as life-threatening organ dysfunction caused by a dysregulated host response to infection. "A recent study investigated the role of TTC4 in sepsis-induced acute lung injury (ALI) focussing on its interaction with HSP70 and its impact on pyroptosis." (PMID 40313865, 2025). "Downregulation of TTC4 was observed in both patients with sepsis-induced ALI and a mouse model." (PMID 40313865, 2025). "Moreover, the m6A-forming enzyme METTL3 reduced TTC4 stability, suggesting a regulatory mechanism in sepsis-induced ALI." (PMID 40313865, 2025).
tumor (5 papers, 2008 to 2019). "TTC4 is also a potential Hsp90 binding protein and appears to have an important role in linking Hsp90 function to replication, TTC4 may thus have a role in multiple nuclear functions including transcription and replication and these may be linked to its tumor suppressor properties." (PMID 24278769, 2013). "Others such as the J domain protein family, HspBP1, TTC4, and FKBPL appear to be associated with more benign tumor phenotypes." (PMID 24278769, 2013). "A comparison was also made of the level of the TTC4 protein in normal (MRC5 fibroblasts) versus tumour derived cell lines." (PMID 18320024, 2008). "Such information is necessary in order to propose a meaningful model for TTC4 action during tumour development." (PMID 18320024, 2008). "It is therefore possible to suggest that an increased level of TTC4 contributes to the development of a variety of different tumours." (PMID 18320024, 2008). "Furthermore increases in TTC4 protein levels are also observed in a number of other tumour derived cell lines compared to normal cells and tissues." (PMID 18320024, 2008). "We also see increased TTC4 expression in a variety of tumour lines derived from other tissues." (PMID 18320024, 2008). "However, a sizable number of the co-chaperones, including HspBP1, the JDP family proteins, FKBPL, and TTC4 appear to signal a good prognosis in cancer suggesting that they may have tumor suppressive functions." (PMID 24278769, 2013). "TTC4 therefore shows altered expression in all tumour lines studied but none of the normal cell lines (fibroblasts, Nohm1 and Hermes 3a melanocytes) suggesting that alterations in TTC4 expression may be related to a change in property of the cells." (PMID 18320024, 2008). "Although the precise role for TTC4 in tumour development is not clear, it may be partly related to a loss of protein interactions." (PMID 18320024, 2008).
cancer (2 papers, 2008). A tumor composed of atypical neoplastic, often pleomorphic cells that invade other tissues. "Data presented in this paper also suggests that TTC4 is involved in the development or progression of cancer." (PMID 18320024, 2008).
TTC4 also shares sentences with these, for which no sentence is quoted: diabetes (2 papers); atopic dermatitis (1); ciliopathy (1); colon carcinoma (1); glioma (1); infection (1); lung adenocarcinoma (1); type 2 diabetes (1).